CDH13 (cadherin 13)
Diseases named in the same sentence as CDH13 in open-access papers (continued):
Sharing a sentence is not in itself a finding about the gene and the disease.
tumor (continued). "Concordantly hypermethylated CpGs were associated with genes involved in Cadherin, Wnt and Notch signaling pathways, many of which have been previously reported as frequently methylated in a variety of neoplasms, such as APC2, SFRP2, CDH13, CDH15 and PCDH10." (PMID 22737091, 2012). "Using pyrosequencing, we measured the methylation status of 6 putative tumor-suppressor genes HIN-1, CDH13, RIL, RASSF1A, RARβ2, and E-cadherin." (PMID 20642860, 2010). "RASSF1A, RARβ2, E-cadherin (CDH1), CDH13 and RIL were found to be expressed at a low level, in agreement with the hypermethylation of these genes in tumor tissues." (PMID 20642860, 2010). "Twelve tumor-suppressor genes: ARHI, RASSF1A, HIN-1, RARβ2, hMLH1, 14-3-3 σ, RIZ1, p16, E-cadherin, RIL, CDH13, and NKD2 were selected for this methylation study." (PMID 17764565, 2007). "We evaluated the methylation status of 12 putative tumor-suppressor genes (ARHI, RASSF1A, HIN-1, RARβ2, hMLH1, the 14-3-3 σ gene, RIZ1, p16, the E-cadherin gene, RIL, CDH13, and NKD2), LINE1, ER, and PGRB in both culture cell lines and primary cancer tissues." (PMID 17764565, 2007). "Finally, FAP was associated with ECM and adhesion genes (FN1, COL5A1, SPOCK1, CDH13) and regulators of migration (NREP, SEMA5A), consolidating its central role in matrix deposition and tumor invasion, as previously shown." (PMID 41198614, 2025). "As expected, CDH13 methylation was absent in tumor-adjacent (morphologically normal) tissue, and none of our control samples showed any methylation (cut-off 10%)." (PMID 38926485, 2024). "According to the staining score, CDH13 expression in tumor specimens was lower than that in adjacent nontumorous tissues (P < 0.0001)." (PMID 32127937, 2020). "Moreover, in our cell line and respective primary tumor, we showed that HPV integrates into the CDH13 gene." (PMID 30760827, 2019). "Cadherin 13 (CDH13), a tumor suppressor in various types of cancer, was a direct target of miR-675." (PMID 30217088, 2018). "The methylation statuses of P16, RASSF1A, APC, RARβ, DAPK, CDH13, and MGMT were not linked to age, gender, smoking behavior, and tumor stage and histology in NSCLC." (PMID 28404957, 2017). "Eleven cancer related genes were found to have methylation (defined as more than 10 % methylation) in at least some of the tumours: RASSF1A (64 %), TWIST1 (61 %), CDH13 (51 %), APC (50 %), MAL (35 %), GSTP1 (30 %), WIF1 (26 %), RARβ (19 %), BRCA1 (2 %), CDKN2A (2 %) and TP73 (2 %)." (PMID 26452468, 2015). "Probably, for CDH13, the cutoff value to provide best discrimination between tumor and normal tissue (generally not methylated) should be higher." (PMID 25065733, 2014). "In order to further evaluate CDH13 localization, serial sections of both tumor and matched normal tissue were stained for CD31, a marker of endothelial as well as other blood cells, and CDH13." (PMID 24979721, 2014). "To further examine the relationship between the methylation profile with patient characteristics and tumor markers, we focused on the 4 genes (RASSF1A, RARβ2, CDH13 and SFRP1) that showed the highest relative changes in tissue methylation status across the 65 tissue pairs." (PMID 22701537, 2012). "Similarly, in tumor tissues, a moderate correlation existed between RASSF1A and HIN-1 (R = 0.51, p < 0.001) and a weak correlation existed between RIL and CDH13 (R = 0.19, p = 0.068)." (PMID 17764565, 2007). "Specifically, a patient with a positive value in the RIL/CDH13 panel is ten times more likely to have an ER-negative tumor than a patient with a negative value." (PMID 17764565, 2007). "Up-regulation was also found for cadherin 13, a gene with growth inhibitory functions that is expressed in normal cells but not in the majority of human tumour cells of epithelial origin." (PMID 16001974, 2005).
tumor (continued). "Further, we analyzed whether the methylation status of P16, RASSF1A, APC, RARβ, DAPK, CDH13, and MGMT there were differences in the characteristics of gene methylation in different tumor stages (early stage vs. advanced stage) and tumor histotypes (SCC vs. AC)." (PMID 28404957, 2017). "In addition, both CM presented a remarkable quantity of different proteins that have been associated with antioxidant and/or anti-inflammatory effects and may thus mediate the viability of non-tumor cells, such as AIFM1, ANXA5, CD9, CDH13, GDF15, GSR and TIMP2." (PMID 34884877, 2021).
cancer (97 papers, 2004 to 2026). A tumor composed of atypical neoplastic, often pleomorphic cells that invade other tissues. "Epigenetic alterations, such as promoter hypermethylation of tumor suppressor genes (e.g., APC, TIMP3, CDH13), can serve as biomarkers to identify patients at higher risk of progression from BE to cancer." (PMID 40149421, 2025). "CDH13 expression is linked to immune cell infiltration, affects cancer prognosis and can be downregulated by anti-PD1/CTLA-4/PD-L1 immunotherapy." (PMID 41164751, 2025). "Community 4 members RARB, TIMP3 and CDH13 have been implicated as tumor suppressor gene targets of DNA methylation and epigenetic regulation in cancers." (PMID 39545637, 2024). "Recently, several studies have shown that Cadherin 13 (CDH13, T-cadherin, H-cadherin) functioned as an anti-oncogene and that its polymorphisms were associated with the development of different cancers." (PMID 29416663, 2018). "A recent study has indicated that T-cadherin (also known as H-cadherin and cadherin-CDH13) is associated with malignant tumors." (PMID 28099918, 2017). "Loss of CDH13 expression caused by promoter hypermethylation was observed in breast, lung, colorectal, prostate, and nasopharyngeal cancers." (PMID 26862903, 2016). "e.g. methylation of p16 is a frequent and early event in ESCC, methylation of CDH13 is associated with high grade and advanced stage cancer." (PMID 27286455, 2016). "Cadherins, including CDH13, play an essential role in cell–cell adhesion, and inactivation of this cadherin-mediated cell adhesion due to cadherin downregulation is associated with cancer progression." (PMID 38926485, 2024). "CDH13 (T-cadherin, H-cadherin) is located on chromosome 16q24.2 and is an atypical member of the cadherin family and is closely linked to clinicopathological features and the prognosis of many types of cancer." (PMID 39179585, 2024). "Recent studies have reported that downregulation of H-cadherin in cancers is associated with CDH13 promoter hypermethylation, which could be affected by the single nucleotide polymorphisms (SNPs) near CpG sites in the CDH13 promoter." (PMID 29416663, 2018). "CDH13 (cadherin 13) is a special cadherin cell adhesion molecule, and the methylation of its promoter causes inactivation in a considerable number of human cancers." (PMID 27153114, 2016). "In recent years, the associations of CDH13 with human cancers have been proposed." (PMID 24466011, 2014). "CDH13 is known to be downregulated in various cancers, and CDH13 promotor methylation has been suggested to act in CRC initiation and progression." (PMID 39859530, 2025). "Given that this ncRNA epigenetic circuitry governs CDH13 expression across cardiovascular and metabolic disorders and cancer, targeting these key ncRNA pathways offers a promising strategy to reestablish T-cadherin/CDH13 protective functions in disease." (PMID 40649905, 2025). "Cadherin 2 (CDH2, N-cadherin) and cadherin 13 (CDH13, T-cadherin, H-cadherin) affect the progress and prognoses of many cancers." (PMID 39545598, 2024). "For instance, CDH13 hypermethylation in the promoter region has been reported in several types of cancer, including, CRC, pituitary adenoma, and breast cancer." (PMID 37901797, 2023). "The methylation of the CDH13 promoter in patients with stage I NSCLC who underwent surgery with the intention of curing the cancer was more likely to recur early." (PMID 37901797, 2023). "The top 10 frequently affected cancer-associated genes are HIRA (OG), CSMD1 (TS), CDH13 (TS), PRRX1 (OG), FHIT (TS), MGAM (OG), TBL1XR1 (OG), RHOA (OG), FGF14 (TS), and CNTNAP2 (TS)." (PMID 35013466, 2022).
cancer (continued). "For instance, cadherin-13 (CDH13) inhibits cancer cell invasion and is decreased in fibrotic alveoli." (PMID 35852874, 2022). "There were only 7 (10%) and 2 (3.0%) cases that had a similar or higher expression of CDH13 in cancer tissues, respectively." (PMID 32127937, 2020). "In contrast, CDH13 was reported to have important regulatory roles in human cancers based on a significant correlation of DNA methylation in the CDH13 promoter with the occurrence, development and prognosis of disease." (PMID 33193625, 2020). "Cadherin 13 (CDH13, T-cadherin, H-cadherin) has been identified as an anti-oncogene in various cancers." (PMID 29416663, 2018). "CDH13, a member of the cadherin gene superfamily has been mapped to 16q24, a locus that frequently undergoes deletion in human cancers." (PMID 30355852, 2018). "Given that CDH13 promoter methylation is the most common genetic inactivation event found in human tumors, it would be a useful marker for the early detection of cancer." (PMID 27153114, 2016). "DNA methylation changes in the CDH13 promoter region are well characterized in the development of various cancers." (PMID 25543204, 2015). "A considerable number of human cancer genomes are characterized by hypermethylated CDH13 promoter, and down-regulation of its transcription promotes tumor growth and invasiveness." (PMID 25543204, 2015). "Treatment with DNA methylation inhibitors can restore the activities of CDH13 gene and decrease the growth rate of cancer cells." (PMID 15292927, 2004). "Treatment with DNA methylation inhibitors can restore the activities of the CDH13 gene and decrease the growth rate of cancer cells." (PMID 14997203, 2004). "Clarifying whether miR-199b regulates CDH13 expression during oncogenesis and whether manipulating this miRNA could yield therapeutic benefit represents an intriguing direction for future cancer research." (PMID 40649905, 2025). "Several studies have shown that CDH13 inhibits cancer cells." (PMID 39179585, 2024). "Thus, we analyzed the methylation levels of CDH13 in several cancers using the EWAS Data Hub database (ENSG00000140945)." (PMID 39179585, 2024). "Due to this, CDH13 is a potential therapeutic target for some cancers." (PMID 33407434, 2021). "CDH13 is an atypical member of the cadherin family, without transmembrane domain which has been associated with poorer prognosis in various cancers." (PMID 34139994, 2021). "Furthermore, the level DNA methylation in the promoter of CDH13 is often high during cancer processes." (PMID 33193625, 2020). "Interestingly, cancer genes CDH13 and BCAR1 were found with multiple KRT DhMRs, and they were also important genes for hyper-5hmC in HPV(−) tumors, which is consistent with the previous finding that the KRT subtype shares more similarities with HPV(−) HNSCC." (PMID 33203436, 2020). "As an anti-oncogene, the downregulation of Cadherin 13 expression would promote cancer progression." (PMID 29416663, 2018). "However, CDH13 expression was generally down regulated by CDH13 promoter hypermethylation in human cancers." (PMID 26862903, 2016). "The aberrant methylation of H-cadherin (CDH13) commencing at an early stage of colorectal tumorigenesis frequently silences, in fact, the expression of this tumor suppressor gene in colorectal adenomas and cancers." (PMID 26862732, 2016). "Methylation of the tumor suppressor gene H-cadherin (CDH13) has been reported in many cancers." (PMID 27578166, 2016). "For example, frequent hypermethylation of CDKN2A, RASSF1, CDH13, and other genes has been observed in sputum samples from cancer-free smokers, suggesting that they may be hypermethylated early." (PMID 21577262, 2011). "Thus, CDH13 and its ANGs may regulate the proliferation, invasion, migration, and angiogenesis of cancer cells by affecting integrin function, gene transcription, ability metabolism, and amide and phospholipid metabolism." (PMID 39545598, 2024).
cancer (continued). "Interestingly, CDH13 is generally lost in cancer, including PCa, due to promoter hypermethylation." (PMID 26924072, 2016). "Four genes (CDH13, CYB5R2, RARB2 and SPARC) showed the expected significant hypermethylation (p < 0.05) in cancer patients compared with HDs, whereas DRD2 and LINE-1 were hypomethylated (p < 0.05), as anticipated." (PMID 41008642, 2025). "Our transcriptomic analyses of CM-treated HOSEs uncovered gene-expression profiles defining responses to cancer-like TME, highlighted by STAT1, ISG15, and OAS1 in HOSE1C and ITGA2, GREM1, and CDH13 in HOSE2C." (PMID 39634630, 2024). "CDKN2A (p16), used as a key biomarker for HPV status, exhibited the most extensive hyper-5hmC in HPV(+) tumors, while HPV(−) tumors showed hyper-5hmC in CDH13, TIMP2, MMP2 and other cancer-related genes." (PMID 33203436, 2020). "Four of the genes (RARβ2, SPARC, CDH13, CYB5R2) showed significantly higher methylation in the cancer cases when compared with the control cases (p<0.05)." (PMID 30204798, 2018). "Cadherin 13 (CDH13), a member of the cadherin superfamily, is frequently hypermethylated in various types of cancer including BCP-ALL and was selected to evaluate CpG demethylating effects of HMA." (PMID 29728108, 2018). "The cumulative effect analyses by considering multiple CpG sites in each gene also demonstrated an obvious difference of methylation levels between normal and cancer samples (CASZ1: P 0.001, CDH13: P 0.001, ING2: P 0.001)." (PMID 30355852, 2018). "Our demonstration that the putative tumor suppressor Cdh13 is hypermethylated and downregulated in the lung tumors of old mice suggest that cell intrinsic epigenetic modifications may influence cancer progression in older animals, consistent with epigenetic studies in human cancers." (PMID 29047229, 2018). "Aberrant methylation of p16, RARβ2, CDH13, and RASSF1A genes has also been found in specimens of bronchial epithelial cells from cancer-free heavy smokers." (PMID 29796116, 2018). "p16, TFPI2, the cadherins E-cadherin and CDH13, and the secreted frizzle-related proteins (SFRPs) SFRP1 and SFRP5 were desilenced in cancer cell lines." (PMID 23593653, 2013). "Recently a report examining the methylation of CDH13, CDKN2A/p16, FHIT, RARB, RASSF1A and ZMYND10 (BLU) in which methylation of any 2 loci in plasma was considered cancer positive showed 73% sensitivity and 82% specificity." (PMID 18947422, 2008). "Several frequently methylated loci identified in early studies, for example CDKN2A/p16, CDH13, MGMT and RASSF1 remain viable markers when assessed in a larger context, providing support for their role in cancer development/progression." (PMID 18947422, 2008). "Therefore, lncRNA LIMT can be seen as a tumor suppressor by preventing miR-665 from binding to the mRNAs of the two anti-cancer genes, MAP4K3 and CDH13." (PMID 37894282, 2023). "Plasma methylation of HPV genes, including L1, as well as promoter methylation of CADM1, CDH1 (promoter for E-cadherin), and CDH13 (cadherin-13), among others, readily distinguishes between cancer and benign/no disease controls." (PMID 38958745, 2023). "The analyzed genes in this work (SOX17, MYOD1, MAGI2, CDH1, AJAP1, MGMT, CDH13, and RASSF1A) participate in essential biological processes to maintain cell normality, and there is sufficient evidence for their protective role against the development of cancer." (PMID 34991696, 2022). "Moreover, we implicate several of these gene hits not only in ccRCC for the first time (BHLHB3, CAMK1, CDH13, ENPP3, KCNJ2, KSR1, PLOD2, and TCF8), but also in a cancer model for the first time (CEP290, EFCAB3, PGBD5, RAPGEF5, SSPN, and TOX2)." (PMID 24979721, 2014). "In addition, CDH13 and RIL methylation levels cancers were marginally higher in poorly differentiated than well- and moderately differentiated cancers (p = 0.059 and 0.096, respectively)." (PMID 17764565, 2007).
cancer (continued). "TaqMan® PCR experiments performed for two of these molecules, CDH13 and PLAU, corroborated array results revealing significant expression levels differences between the two cancer types, not only in the cell lines, but also in an additional set of primary 14 PDTC and three ATC." (PMID 17406368, 2007). "Given that cancer cell clusters in pLN+ OSCC are ‘TGF‐βI positive’ with enriched EMT functions, we speculate that TGF‐βI is involved in upregulating EMT by inducing the marker genes in these subclusters, such as COL17A1, ITGA6 and CDH13." (PMID 40038875, 2025). "We observed an inverse correlation between CDH13 methylation (p = 0.045; r = -0.21) and serum vitamin D level whereas TIMP3 methylation (p = 0.021; r = -0.24) and DRD2 methylation (p = 0.056; r = -0.201) showed inverse correlation with supplementary vitamin D in the cancer cases." (PMID 30204798, 2018). "Besides, other studies have identified genes with significantly different methylation between different subtypes, and the differentially methylated genes (including CDKN2A, APC, CDH13, THBS2 and ERG) have been utilized to distinguish these different histological subtypes of cancers." (PMID 26862903, 2016). "Therefore, it might be possible that the CDH13 gene expression has not been inhibited completely in these cancers." (PMID 15292927, 2004).
cardiovascular disease (16 papers, 2013 to 2026). "CDH13 plays essential roles in the development of the neurological and vascular systems and is a risk factor for neural and cardiovascular diseases." (PMID 42200830, 2026). "The genetic variations occur in CDH13, which is implicated in cardiovascular disease by multiple GWAS." (PMID 40892706, 2025). "FAVs that associate with the gut yeast Kazachstania consistently link with genetic variation in CDH13 which codes for T-cadherin and phenotypes of cardiovascular disease risk." (PMID 40892706, 2025). "CDH13 is expressed in multiple tissue types, including cardiomyocytes, blood vessels, and intestines, and disruption of T-cadherin’s interactions with adiponectin increases the risk of cardiovascular disease." (PMID 40892706, 2025). "In this study, we investigated functional relationship between three protein-coding genes genetically associated with cardiovascular disease, i.e., CDH13, SLC12A3, and CKAP5, and their intronic miRNAs using a data-driven approach." (PMID 31464655, 2019). "Notably, the relative abundance of gut yeast Kazachstania associates with genetic variation in CDH13 encoding T-cadherin, a protein linked to cardiovascular disease." (PMID 40892706, 2025). "Thus, variants in the CDH13 gene are pro-atherogenic that can, in turn, heighten cardiovascular disease risk." (PMID 40892706, 2025). "Additionally, single nucleotide polymorphism (SNPs) in CDH13 gene encoding T-cadherin strongly correlates with plasma adiponectin level and cardiovascular diseases in humans." (PMID 39717846, 2024). "Mendelian two-sample randomization and prior clinical evidence further implicate Kazachstania and genetic variation in CDH13 to cardiovascular disease." (PMID 40892706, 2025). "The HYPEST/CADCZ cardiovascular diseases samples were targeted to fine scale analysis of CpG sites at the CDH13 promoter using resequencing and the EpiTYPERTM assay." (PMID 25543204, 2015). "However, none of these three patients with cardiovascular disease were included in the TMT Labeling proteomic studies, and cardiovascular disease did not impact cadherin-13 levels in plasma." (PMID 38791465, 2024).